IL18 (interleukin 18)
Diseases named in the same sentence as IL18 in open-access papers (continued):
Sharing a sentence is not in itself a finding about the gene and the disease.
pulmonary fibrosis (continued). "Therefore, we hypothesized that tetracycline reduces silica-induced lung injury and lung fibrosis resulting from chronic silicosis via limiting IL-1β and IL-18 driven inflammation." (PMID 35130879, 2022). "Nevertheless, the scutellarin treatment dose-dependently reduced the production of inflammatory cytokines IL-1β and IL-18, suggesting that the scutellarin could deliver anti-inflammatory function in pulmonary fibrosis in vitro and NF-κB/NLRP3 pathway might participate in this regulation process." (PMID 33188176, 2020). "Importantly, Il-18 has also been shown to stimulate fibroblast proliferation and collagen synthesis and has been associated with obstructive lung diseases such as COPD and pulmonary fibrosis." (PMID 25710175, 2015). "In light of IL-18’s demonstrated capability to modulate the T-cell phenotype by eliciting IFN-γ, we have posited a novel therapeutic approach for pulmonary fibrosis." (PMID 38300690, 2024). "SS-31 treatment significantly attenuated pulmonary fibrosis and inflammation induced by BLM, with reduced expression of IL-1β and IL-18." (PMID 38136142, 2023). "In the BLM-induced pulmonary fibrosis model mice and BLM-stimulated PAECs, TA293 suppressed the expression of Il1b and Il18 mRNAs, but mitoTA293 increased their expression levels." (PMID 34573030, 2021). "Neutralization of IL-13 during the Ag plus IL-18 challenges inhibited eosinophilic infiltration, lung fibrosis, and periostin deposition; while neutralization of IFN-γ during the Ag plus IL-18 challenges inhibited neutrophilic infiltration and AHR." (PMID 25981515, 2015). "To test this hypothesis, we enhanced the P2RX7/IL-18 axis in the BLM-induced lung fibrosis mouse model by using HEI3090, a chemical compound described to stimulate immune cells expressing P2RX7 to generate IL-18 in the presence of eATP." (PMID 38300690, 2024). "The absence of NLRP3 and IL-18 in P2RX7-expressing immune cells abrogated the ability of HEI3090 to inhibit lung fibrosis because the lung architecture and collagen fibers intensity resembled that of control mice." (PMID 38300690, 2024). "IL-18 inhibits cytotoxic cells to regulate alveolar septal destruction and airway fibrosis, and, notably, IL-18-induced progression of pulmonary fibrosis was alleviated in the absence of BRP-39, a downstream effector of IL-18." (PMID 39068486, 2024). "However, IL-18 accelerates fibroblast aging and exacerbates fibrosis in the lungs of mice with BLM-induced pulmonary fibrosis." (PMID 34573030, 2021). "However, IL-18 was expressed during bleomycin and viral-induced lung fibrosis in alveolar and interstitial immune cells but absent from mesothelial cells during injury." (PMID 39747171, 2025). "Similarly, stimulation of the AIM2 receptor with Poly dA:dT for 5 hours did not lead to the release of IL-18 from PBMCs from PC patients without or with signs of lung fibrosis." (PMID 35844548, 2022). "Indeed, in our experimental model of bleomycin-induced pulmonary fibrosis (measured by collagen deposition around the airways), we observed that IL-1β, rather than IL-18, as observed in humans, is upregulated in mRNA levels after bleomycin treatment." (PMID 29675024, 2018).
Still’s disease (40 papers, 2011 to 2025). "Beyond, we cannot identify a significant association of seropositivity for anti-IL-1Ra antibodies with Still’s disease hallmark cytokine levels such as IL-6 or IL-18." (PMID 38231276, 2024). "Thus, NLRC4 mutations can result in overwhelming production of IL-18, as in systemic juvenile idiopathic arthritis (sJIA) and adult onset still’s disease, in which NLRC4 mutations drive IL-18 production into the nanogram range, due to uninhibited production." (PMID 36823262, 2023). "High concentrations of IL-18 have been found in patients with Crohn’s disease, asthma, chronic obstructive pulmonary disease, systemic juvenile idiopathic arthritis, and Still’s disease." (PMID 40429966, 2025). "Various cytokines have been investigated as biomarkers of Still’s disease, with several studies suggesting that IL-18 is a potential biomarker and an indicator of disease activity." (PMID 38756937, 2024). "A defect in IL-18-induced IFN-γ by NK cells has been described in patients with systemic juvenile idiopathic arthritis (sJIA), an autoinflammatory rheumatological disease that is associated with development of MAS." (PMID 36275702, 2022). "A human recombinant form (Tradekinig Alfa, AB2 Bioltd) is currently under evaluation in treatment of Still's disease and hemophagocytic lymphohistiocytosis syndrome, that is to say a pathology in which the IL-18/IL-18R axis seems preponderant." (PMID 31507607, 2019). "Ferritin is increased at levels often exceeding 4000 ng/ml in autoinflammatory syndromes like Still’s disease and acute gouty arthritis that are mediated through excess production of IL-1β and IL-18." (PMID 28918754, 2017). "Interestingly, IL-18 is found to play a key role in the pathogenesis of Still's disease and is correlated with raised serum ferritin levels." (PMID 40557016, 2025). "Chen and colleagues investigated the relationship between galectin-3 levels and disease activity in Still’s disease, an autoinflammatory disease, and reported that galectin-3 levels were elevated in these patients and positively correlated with IL-1β and IL-18 levels." (PMID 41008774, 2025). "As expected, patients with rheumatologic hyperferritinemia (Stills Disease) had significantly higher total IL-18 (including free IL-18 and IL-18 in complex with IL-18BP) values, both per sample and maximum, compared to the infection and immune dysregulation subgroups." (PMID 39264477, 2024). "Systemic-onset juvenile idiopathic arthritis (SoJIA) represents an inflammatory systemic disorder largely due to a dysregulation in innate immunity pathways, especially involving pro-inflammatory cytokines such as IL-1, IL-6, and IL-18." (PMID 37189714, 2023). "In addition, markedly elevated plasma IL-18 levels are present in patients with systemic juvenile idiopathic arthritis (sJIA) or systemic inflammatory adult-onset Still's disease (AOSD), which are at high risk of developing life-threatening MAS." (PMID 33823154, 2021). "The aim of this research was to explore whether IL-18 can be a serological marker for the diagnosis of systemic-onset juvenile idiopathic arthritis (sJIA)." (PMID 28225869, 2017). "Thus, IL-18 may be useful both diagnostically and in assessing minimal residual disease activity in Stills disease." (PMID 39264477, 2024). "The adult and juvenile forms of Still’s disease, AOSD and sJIA, involve extremely high levels of IL-18." (PMID 39769266, 2024). "In contrast, in systemic juvenile idiopathic arthritis, CD56(bright) NK cells have decreased granzyme K expression and IL-18-driven IFN-γ production, which demonstrated the multi-function role of NK cells in autoimmune arthritis." (PMID 35432322, 2022). "Inflammasome activation seem to play an important role in systemic Juvenile Idiopathic Arthritis (SJIA) pathophysiology, characterized by high levels of IL-18 and IL-1 pathway activation." (PMID 36096831, 2022).
Still’s disease (continued). "Our study also revealed that the serum Gal-3 levels were highly correlated with the serum IL-18 levels, which are presumed to be useful biomarkers for autoinflammatory diseases, such as AOSD, systemic juvenile idiopathic arthritis, and NLRC4 inflammasomopathies." (PMID 38711500, 2024). "On a serum/plasma biomarker level Still’s disease is further hallmarked by elevated levels of bioactive, free IL-18 (not complexed by IL-18 binding protein (IL-18BP)); as well as S100 proteins, sCD163, IL-6, IL-8, IL-17, and TNF-α." (PMID 38231276, 2024). "Among other biological markers, interleukin 18 (IL-18) appears as a reasonable candidate for a better understanding of adult-onset Still’s disease (AOSD) and systemic juvenile idiopathic arthritis (sJIA) pathophysiology, evaluation of disease activity, and therapeutic approaches." (PMID 35054124, 2022).
ovarian carcinoma (39 papers, 2009 to 2026). A malignant neoplasm originating from the surface ovarian epithelium. "However, their results failed to support an association between selected polymorphisms at IL-1α, IL-β, IL-6, IL-10, or IL-18 gene and increased risk of ovarian cancer in USA." (PMID 34582655, 2021). "Furthermore, linkage between -137G/C and -607C/A polymorphisms of the IL-18 gene and progression of ovarian cancer and nasopharyngeal carcinoma was reported." (PMID 26376814, 2015). "The results also showed a significantly higher IL-18/IL-18BP ratio for ovarian cancer tissue and significantly higher IL-18BP expression in physiological ovarian tissue." (PMID 41561739, 2025). "Ex vivo activation of NK cells with cytokines like IL-2, IL-12, IL-15, or IL-18 enhances proliferation, cytokine secretion, and the ability to lyse ovarian cancer cell lines, even those with low MHC-I expression." (PMID 41375063, 2025). "In ovarian cancer, NK cells stimulated with IL-12, IL-15, and IL-18, known as CIML NK cells, have shown promising clinical trial results." (PMID 41375063, 2025). "Relatedly, anti-inflammatory evidence of withaferin A has been shown in ovarian cancer cells by suppressing the secretion levels of various pro-inflammatory cytokines, such as tumor necrosis factor-alpha (TNFα), IL-6, IL-8, and IL-18 in ovarian cancer cells." (PMID 37110423, 2023). "Our observations showed an increase in IL18 gene expression in fibroblasts as a result of treatment with exosomes from ovarian cancer cells." (PMID 36012171, 2022). "Exosomes from both studied ovarian cancer lines treated simultaneously with α-mangostin and cisplatin contributed to the smallest increase in IL18 expression." (PMID 36012171, 2022). "Although the exact role of IL18 has not yet been investigated, studies have shown that the serum levels of IL18 in patients with ovarian cancer were elevated compared to controls." (PMID 36012171, 2022). "Our results showed that treatment of fibroblasts with exosomes from ovarian cancer cells also changed the expression of the IL18 gene." (PMID 36012171, 2022). "(H, I) Immunohistochemical analysis of IL20RA, p-STAT3, OAS1, and IL-18 in human primary ovarian cancer tissues (Pri) and paired peritoneal metastatic nodules (Met) (H) and quantification (I)." (PMID 34114949, 2021). "IL-18 is the essential factor downstream IL-20/IL20RA signaling to prevent the ovarian cancer dissemination." (PMID 34114949, 2021). "We observed the association of SUCNR1 expression with interleukins, including IL1B (cor = 0.473, p = 2.86e-18), IL7 (cor = 0.39, p = 1.78e-12), IL16 (cor = 0.508, p = 2.66e-21), and IL18 (cor = 0.348, p = 4.67e-10), in ovarian cancer." (PMID 33062639, 2020). "Chang used expression profiling to identify mechanisms involved in the malignant transformation of endometriosis to ovarian cancer; 18 genes were identified, including NLRP3, IL-1B, and IL-18, which implicated inflammasomes." (PMID 31923221, 2020). "Third, the serum levels of IL-18 were found to be higher in cancer patients than in healthy subjects, including bladder cancer, ovarian cancer, gastrointestinal cancer, and non-small cell lung cancer." (PMID 30925760, 2019). "We previously showed that IL-27, similar to IFN-γ, upregulated the expression of IL-18BP, a natural inhibitor of IL-18 activity, in ovarian cancer cells, and that IL-18BP protein accumulates in the ascites of patients." (PMID 28255204, 2017). "For instance, the pro-inflammatory cytokine IL-18 has been combined with chemotherapeutic agents for the treatment of the murine spontaneously tumorigenic MOSE ovarian cancer cell line ID8." (PMID 27854240, 2016). "We reported that IL-27 induces the expression of the IL-18 inhibitor IL-18BP, in human Epithelial Ovarian Cancer (EOC) cells, thus potentially limiting the immune response." (PMID 26657115, 2015).
ovarian carcinoma (continued). "Immunohistochemical analyses have shown differential expression of IL-18 and its receptors in benign ovarian tumors, borderline ovarian tumors, and ovarian carcinomas." (PMID 25403235, 2014). "Since IL-18 mRNA and IL-18 protein were detected in primary ovarian cell cultures, it is reasonable to assume that the elevated IL-18 levels in ovarian cancer patient sera are produced by ovarian carcinoma cells as well as tumor-activated immune cells." (PMID 24963217, 2014). "It is still unclear; however, which cell population is responsible for the elevated IL-18 levels in the sera of ovarian cancer patients and how IL-18 influences the development and progression of EOC." (PMID 24963217, 2014). "Proinflammatory cytokine IL-18 has been shown to be elevated in the sera of ovarian carcinoma patients." (PMID 24963217, 2014). "The circulating levels of IL-18 are increased in patients with epithelial ovarian cancer compared to healthy controls and patients with borderline ovarian tumors and early-stage carcinoma." (PMID 24963217, 2014). "Chemotherapeutric agents with measured time-dependent immune-enhancing effects were then tested for antitumor effectiveness in vivo in combination with IL-18 immunotherapy using the ID8-Vegf ovarian cancer model." (PMID 21609494, 2011). "Accordingly, the capacity to provide super-physiological concentrations of IL-18 through passive cytokine administration provides the opportunity to promote antitumor responses in patients with ovarian cancer in vivo." (PMID 20003308, 2009). "A similar level of survival was obtained with combination Doxil at 2.5 mg/kg with IL-18 at 100 μg suggesting that the efficacy of Doxil therapy for ovarian cancer can be improved by the addition of IL-18." (PMID 20003308, 2009). "NLRP3, IL-1β, and IL-18 are upregulated during transformation of endometriosis to ovarian cancer." (PMID 39769450, 2024). "Supporting our hypothesis of indirect NK cell interference, we showed that the NK-activating cytokine IL18 is enhanced in the supernatants of sensitized ovarian cancer cells." (PMID 31546690, 2019). "However, the regulatory pathways for IL-18 production by both ovarian carcinoma cells and tumor-induced host cells and its mechanisms of action remain to be determined." (PMID 24963217, 2014). "Therefore, it seems reasonable to assume that IL-18 is more potent/active in ovarian carcinoma cells." (PMID 24963217, 2014). "Ovarian carcinoma expresses IL-18, but it is predominantly the pro-IL-18 form." (PMID 20356397, 2010). "The favorable safety profiles of both IL-18 and Doxil, coupled with the potent therapeutic effect of their combination reported herein, warrants the clinical evaluation of this combinatorial approach in ovarian cancer." (PMID 20003308, 2009). "In ovarian cancer, IL-18 single nucleotide polymorphism (SNP) analysis does not reveal evidence for an association with epithelial ovarian cancer risk." (PMID 20003308, 2009). "However, some PYAGs with CNV gain, such as GSDMD, TP63, PRKACA, PJVK and CASP4, showed downregulated mRNA expression in ovarian cancers, and some PYAGs with CNV loss, such as IL18, GPX4, GZMA, NLRP6 and CASP6, showed upregulated mRNA expression in ovarian cancers." (PMID 36707884, 2023). "In addition, others have shown synergistic effect of IL-27 with IL-18 in NK cells and IL-27 dependent up-regulation of IL-18bp in human ovarian cancer cells and skin resident cells, suggesting some interactions between IL-27 and IL-18 during inflammation and immune responses." (PMID 34663245, 2021). "Therefore, the downregulation of MHC I on tumor cells as well as enhanced release of the NK-stimulating cytokine IL18 out of ovarian cancer cells may be crucial." (PMID 31546690, 2019).
ovarian carcinoma (continued). "Exosomes from SKOV-3 and TOV-21G ovarian cancer cells increased the expression of mouse double minute 2 homolog (MDM2) and interleukin 18 (IL-18) in fibroblasts but were reduced after α-mangostin (12.5 and 29.98 μM) treatment on gene expression in fibroblasts." (PMID 39595559, 2024). "Combined anti-CD47 therapy with olaparib also reduced cytokine secretion of IL6, IL18 and CCL2 from ovarian cancer cells." (PMID 37468567, 2023). "NK cell‐mediated immunity removes ovarian cancer via cytokine‐induced memory‐like NK cells, which generate IFN‐γ and TNF‐α after seven days of IL‐18 exposure." (PMID 37752941, 2023). "In our study, we observed an increase in the expression of VEGFA and three cytokines (IL18, CCL7 and CXCL12) in fibroblasts after treatment with exosomes derived from ovarian cancer cells." (PMID 36012171, 2022). "More recently, Uppendahl and colleagues demonstrated enhanced functionality and cytotoxicity of peritoneal NK cells against ovarian cancer cells after activation with IL12, IL15, and IL18." (PMID 34187852, 2021). "In ID8 murine ovarian cancer cells, the combination of chemotherapeutic PLD and the immunotherapy Interleukin 18 (IL-18) resulted in enhanced tumor suppression relative to either agent as a monotherapy." (PMID 25806106, 2015). "As an upregulated lncRNA in ovarian cancer tissues and cell lines, HOTTIP silencing leads to NLRP1 inflammasome-mediated pyroptosis, decreases cell viability, increases the expression of pro-pyroptosis factors, like IL-18, IL-1β, and NLRP1, and activates caspase-1 in ovarian cancer cells." (PMID 39967908, 2025). "Similarly, IL-27 was found to induce the expression of immune-regulatory molecules such as IL-18BP, the natural inhibitor of IL-18, and PD-L1 and IDO in human ovarian cancer cells and also in other cancer cells in vitro." (PMID 28255204, 2017). "Irrespective of its biological activity, IL-18 concentration significantly increases in the blood of ovarian carcinoma patients." (PMID 24963217, 2014). "Based on these findings, a phase I trial was performed of recombinant human IL-18 in combination with PEGylated Liposomal Doxorubicin (PLD), which resulted in a 6% partial objective response rate and a 38% stable disease rate in subjects with recurrent ovarian cancer." (PMID 27854240, 2016). "Furthermore, cytokines such as interleukin 18 (IL-18) and stroma derived factor 1 (SDF-1) have been shown to be correlated with poor prognosis in ovarian cancer patients, but further studies are required to fully evaluate them in the tumor microenvironment and the periphery." (PMID 21318181, 2010).